RNU6-624P (RNA, U6 small nuclear 624, pseudogene)
Gene: Small nuclear RNA gene on chromosome 2 (228,169,743 to 228,169,849, forward strand). Ensembl gene ENSG00000200281.
Homologues: Orthologues: chimpanzee U6 (100% identical), macaque U6 (93% identical). Paralogues in human: RNU6-1145P (84% identical), RNU6-434P (84% identical), RNU6-46P (84% identical), RNU6-836P (84% identical), RNU6-1081P (83% identical), RNU6-10P (83% identical), RNU6-1316P (83% identical), RNU6-38P (83% identical), RNU6-393P (83% identical), RNU6-1124P (82% identical), RNU6-116P (82% identical), RNU6-1227P (82% identical), and 1283 more.